IQGAP1 (IQ motif containing GTPase activating protein 1)
Diseases named in the same sentence as IQGAP1 in open-access papers (continued):
Sharing a sentence is not in itself a finding about the gene and the disease.
hepatocellular carcinoma (24 papers, 2010 to 2025). A malignant tumor that arises from hepatocytes. "IQGAP1 mRNA/protein levels are upregulated in hepatocellular carcinoma (HCC), a cancer type where loss of the core proteins of the Hippo pathway and upregulation of YAP1 proliferative signal have been shown to result in cancer development." (PMID 33672268, 2021). "This facilitates tumor cell migration and invasion, as seen in hepatocellular carcinoma, where IQGAP1 enhances Rac1-dependent Src/FAK signaling." (PMID 41035668, 2025). "IQGAP1 modulates mTOR signaling, supporting Akt phosphorylation and promoting tumor progression, particularly in hepatocellular carcinoma." (PMID 41035668, 2025). "Higher expression of IQGAP1 was found in hepatocellular carcinoma than adjacent normal tissues, and the expression was related to poor clinical outcomes and postoperative recurrence in patients." (PMID 39073693, 2024). "IQGAP1 knockdown in HepG2 hepatocellular carcinoma cells significantly increases HGF-stimulated MET activation and signaling to Akt and ERK." (PMID 36766826, 2023). "Consistent with our results, IQGAP1 knockdown in Snu-449 hepatocellular carcinoma cells was recently reported to enhance HGF-stimulated MET activation and phosphorylation of Akt." (PMID 36766826, 2023). "In hepatitis B virus (HBV)-associated hepatocellular carcinoma, the accumulation of ROS induced by HBV enhances the combination of IQGAP1 and Rac1, which activate the Rac1 and Src/FAK pathway to enhance anoikis resistance and the migration of hepatoma cells." (PMID 37049739, 2023). "In the case of IQGAP2 knockout mice, they develop age-dependent hepatocellular carcinoma (HCC) with increased IQGAP1 expression." (PMID 37892237, 2023). "The objective of this study was to determine the outcome of pre-treatment of IQGAP1-shRNA on induced mouse hepatocellular carcinoma model and evaluate the potency of this IQGAP1-shRNA plasmid to recover hepatic cancer as a new tool of cancer therapy." (PMID 36276098, 2022). "The disruption of IQGAP2 in mice promoted the occurrence of hepatocellular carcinoma and was reversed by the deletion of both IQGAP1 and IQGAP2, indicating the opposite biological effects of the two isoforms." (PMID 36275458, 2022). "Of note, IQGAP2 deficiency results in hepatocellular carcinoma in mice, but IQGAP1 and IQGAP2 double disrupted mice have less hepatocellular carcinoma and normal survival." (PMID 34034707, 2021). "Src activation is a well-known pathway for anoikis resistance, and IQGAP1 upregulation in hepatitis B virus-positive hepatocellular carcinoma cells promotes anoikis resistance, migration, and invasion via activation of Src/FAK signaling." (PMID 33440835, 2021). "IQGAP1 overexpression resulted in increased cell proliferation and migration via interaction with β-catenin in hepatocellular carcinoma cells." (PMID 33519917, 2020). "In this study, we have found that IQGAP1 interacts with β-catenin and regulates β-catenin expression in hepatocellular carcinoma (HCC) cells." (PMID 26252773, 2015). "IQGAP1 was found overexpressed in lung, endometrial, ovarian, gastric, colon, and breast cancer, as well as hepatocellular carcinoma (HCC) and melanoma." (PMID 37892237, 2023). "For example, the oncogenes ROCK2 and EZH2 that are direct targets of tumor-suppressive miR-124 in hepatocellular carcinoma, and the IQGAP1 who is directly repressed by miR-124 in HCC cell lines and plays important functions in the cell adhesion and motility." (PMID 25069957, 2014). "There is growing evidence that IQGAP2 is a novel tumor suppressor counteracting the effects of IQGAP1, an oncogene, in several cancers, especially in hepatocellular carcinoma (HCC)." (PMID 22973521, 2012). "In hepatitis B virus (HBV)-positive hepatocellular carcinoma (HCC), IQGAP1 is upregulated by increased reactive oxygen species (ROS) levels, which promotes its binding to Rac1 and subsequently activates the Src/FAK signaling axis." (PMID 41035668, 2025).
hepatocellular carcinoma (continued). "IQGAP1 has also been shown to enhance viability and inhibit anoikis by activating Src/FAK signaling in hepatocellular carcinoma, suggesting its potential as a marker for metastasis and prognosis." (PMID 39391236, 2024). "For example, IQGAP1 has been reported to activate the Src/FAK pathway, enhancing cell viability and inhibiting anoikis in hepatocellular carcinoma, making it a valuable indicator of metastasis and prognosis." (PMID 38238592, 2024). "The level expression of IQGAP1 is elevated in many types of cancers, including NSCLC, colorectal carcinoma, hepatocellular carcinoma, thyroid cancer, and pancreatic cancer." (PMID 29596304, 2018). "Mice lacking both Iqgap1 and Iqgap2 display relative protection against hepatocellular carcinoma (HCC) and longer survival compared to Iqgap2-/- mice, implying that at least in the liver IQGAP1 antagonizes activity of IQGAP2." (PMID 26047140, 2015). "Mo reported that IQGAP1 could enhance cell viability and inhibit anoikis by activating the Src/FAK pathway, indicating that it can be a reliable indicator for metastasis and prognosis of hepatocellular carcinoma (HCC)." (PMID 34992654, 2021).
pancreatic cancer (23 papers, 2009 to 2025). "The mechanism of IQGAP1 in pancreatic cancer has been found to be strongly associated with the MAPK pathway." (PMID 41035668, 2025). "In summary our data suggest that in pancreatic carcinoma cells activated Rac1 interacts with IQGAP1, which is associated with a disassembly of E-cadherin-mediated adherens junctions and with increased cell migration and invasion of pancreatic carcinoma cells." (PMID 19737400, 2009). "The stabilising function of IQGAP1 on the turnover of E-cadherin/catenin complexes was underlined by the downregulated IQGAP1 expression by siRNAs which resulted in a disassembly of the E-cadherin/β-catenin complex and reduced concentration of E-cadherin in the analysed pancreatic carcinoma cells." (PMID 19737400, 2009). "IQGAP1 promotes pancreatic cancer progression by increasing the levels of DVL2 protein, enhancing the canonical Wnt/β-catenin pathway, and driving cell migration, invasion, and epithelial-mesenchymal transition (EMT)." (PMID 41035668, 2025). "KRAS mutations activate ARL4C, which recruits MMP14 via its interaction with IQGAP1, forming invasive pseudopodia that contribute to the uncontrolled invasion and metastasis of pancreatic cancer." (PMID 41035668, 2025). "In vitro experiments using a dual-luciferase reporter assay confirmed that SOX4 binds to MAPK1 and promotes its transcription, establishing the role of the SOX4/MAPK1/IQGAP1 regulatory axis in pancreatic cancer cells." (PMID 41035668, 2025). "Phosphoproteomic analysis of pancreatic cancer tissues revealed significantly elevated phosphorylation levels of IQGAP1, and protein blotting results showed that IQGAP1 phosphorylation is regulated by MAPK1 kinase." (PMID 41035668, 2025). "FBP1 increases the sensitivity of pancreatic cancer to gemcitabine by binding to IQGAP1, impeding IQGAP1-dependent ERK1/2 phosphorylation and activation." (PMID 40100307, 2025). "Human pancreatic cancer cells were shown to utilize IL‐6‐mediated Jak2‐STAT3 signaling to form a trimeric complex of Cdc42 with its interaction partner IQGAP1 and STAT3 for IQGAP‐mediated activation of Cdc42." (PMID 33960104, 2022). "The upregulation of IQGAP1 has been recorded in a variety of human cancers, including female-specific tumors (gynecological malignancies), pulmonary cancer, pancreatic cancer, hepatic tumors, CRC, and gastric cancer." (PMID 36276098, 2022). "Overall, these data indicate that MIB1 targets ST7 for degradation, thereby increasing IQGAP1 expression levels and promoting pancreatic cancer progression." (PMID 33793053, 2021). "It was also reported that FBP1 inhibited ERK activation and bypassed gemcitabine resistance in pancreatic cancer by blocking the interaction between IQ motif-containing GTPase activating protein 1 (IQGAP1) and MAPK." (PMID 34363022, 2021). "The knockdown of IQGAP1 reduced cell proliferation and migration in pancreatic cancer cells in a CDC42/RAC1-dependent manner." (PMID 34439095, 2021). "The ability of ST7 silencing to increase pancreatic cancer cell growth was attenuated by the combined silencing of IQGAP1 and ST7." (PMID 33793053, 2021). "These prompted us to study the involvement of ARL4C, as a KRAS downstream molecule, in aggressiveness of pancreatic cancer, and IQ-domain GTPase-activation protein 1 (IQGAP1) was identified as a binding protein of ARL4C." (PMID 34590580, 2021). "In the present study, we identified that by inducing ST7 degradation, MIB1 upregulates IQGAP1 and enhances pancreatic cancer progression." (PMID 33793053, 2021). "(L) Scatter plot showing the correlation between the mRNA expression levels of ARL4C (X-axis) and IQGAP1 (Y-axis) in pancreatic cancer patients obtained from TCGA datasets using the R2: Genomics Analysis and Visualization Platform." (PMID 34590580, 2021). "TCGA dataset revealed that expression of ARL4C mRNA in pancreatic cancer patients is positively correlated with that of IQGAP1 mRNA." (PMID 34590580, 2021).
pancreatic cancer (continued). "Active RAC1 can disrupt the interaction between IQGAP1, E-cadherin and β-catenin and reduce cell–cell adhesion in pancreatic cancer cells." (PMID 34439095, 2021). "Here, we found that the ST7/IQGAP1 axis plays an essential role in pancreatic cancer progression; nevertheless, the mechanism of how ST7 inhibits IQGAP1 requires further investigation." (PMID 33793053, 2021). "IHC staining showed that pancreatic tumors formed by SW1990-shIQGAP1 cells had lower IQGAP1 expression than those formed by SW1990-shNC cells." (PMID 31101875, 2019). "FBP1 overcame gemcitabine resistance and inhibited extracellular regulated protein kinases (ERK) activation by blocking IQ motif containing GTPase-activating protein 1 (IQGAP1)–mitogen-activated protein kinase (MAPK) interaction in pancreatic cancer cells." (PMID 30429463, 2018). "Recent studies implicate a role for IQGAP1 in cancer, with overexpression reported in ovarian, liver, advanced colorectal, thyroid, pancreatic cancer and squamous cell carcinoma." (PMID 25924234, 2015). "Furthermore, the interaction of active Rac1 with IQ motif containing GTPase activating protein 1 (IQGAP1), which is associated with a disassembly of E-cadherin-mediated adherens junctions, has been shown to destabilize E-cadherin-mediated cell-cell adhesion in pancreatic carcinoma cells." (PMID 25452781, 2015). "A previous study indicated that Rac1 destabilizes E-cadherin-mediated cell adhesion in pancreatic cancer by interacting with IQGAP1, thereby promoting cancer cell migration." (PMID 23408967, 2013). "In pancreatic carcinoma cells, another group showed that the binding of IQGAP1 to the β-catenin promotes cell-cell cohesion by stabilizing cell adhesion junction." (PMID 24278215, 2013). "In pancreatic carcinoma cells, IQGAP1 interaction with β-catenin induces the dissociation of VE-cadherin and β-catenin, leading to the adherent junction weakness." (PMID 24278215, 2013). "This reduced interaction between IQGAP1 and β-catenin is associated with destabilised cell-cell adhesion of PANC1 pancreatic carcinoma cells due to reduced amounts of E-cadherin/catenin complexes." (PMID 19737400, 2009). "The GEPIA2 online tool employed to analyze the OS and recurrence‐free survival (RFS) of 30 genes revealed four genes, including CAV1, TMEM43, IQGAP1, and CDK1, that were significantly correlated with pancreatic cancer risk based on their differential expression between tumor and normal tissues." (PMID 40539383, 2025). "In vitro cell experiments confirmed that SOX4 promoted IQGAP1 phosphorylation modification by activating MAPK1 transcription while silencing SOX4 inhibited the proliferation, migration, and invasion of pancreatic cancer cells by reducing the phosphorylation level of MAPK1-IQGAP1." (PMID 38943117, 2024). "Like IQGAP1, it is overexpressed in various types of cancer, including pancreatic carcinoma again suggesting that under‐expression due to genetic variants could interfere with normal migration." (PMID 37635636, 2023). "Importantly, ST7 silencing significantly upregulated IQGAP1, which has been shown to promote pancreatic cancer proliferation." (PMID 33793053, 2021). "Furthermore, we identified ST7 as a critical factor suppressing tumor development and progression by negatively regulating IQGAP1 expression in pancreatic cancer." (PMID 33793053, 2021). "Furthermore, we identified ST7 as a critical factor suppressing tumor development and progression in pancreatic cancer by negatively regulating IQGAP1 expression." (PMID 33793053, 2021). "Knocking down IQGAP1 using shRNA reduced the abilities of pancreatic cancer cells to proliferate and migrate and reduced the incidence of tumor formation and liver metastases in pancreatic cancer xenograft models in vivo." (PMID 34439095, 2021). "IQGAP1 also promotes pancreatic cancer through other pathways." (PMID 34439095, 2021).
pancreatic cancer (continued). "In conclusion, our research shows that the MIB1/ST7/IQGAP1 axis is essential for pancreatic cancer progression, and MIB1 inhibition may serve as a novel therapeutic strategy in patients with pancreatic cancer." (PMID 33793053, 2021). "Thus, simultaneous expression of ARL4C and IQGAP1 would be correlated with aggressiveness of pancreatic cancer." (PMID 34590580, 2021). "Together, the literature suggests that IQGAP1 could be a valuable therapeutic target in treating patients with pancreatic cancer, potentially even those patients with cancers that display intrinsic/acquired drug resistance." (PMID 34439095, 2021). "In conclusion, this study clarified that invasion of pancreatic cancer cells is promoted by ARL4C, of which expression is induced by KRAS and Wnt signaling, and that association of ARL4C with IQGAP1 and MMP14 at the tips of invasive pseudopods are essential for the invasive ability." (PMID 34590580, 2021). "(I) Sections from the pancreatic tumors were stained with anti-IQGAP1 antibody and hematoxylin." (PMID 34590580, 2021). "Furthermore, we found that ST7 suppressed tumor growth by downregulating IQ motif containing GTPase activating protein 1 (IQGAP1) in pancreatic tumor cells." (PMID 33793053, 2021). "Finally, we show that the MIB1/ST7 axis modulates IQGAP1 expression in pancreatic cancer." (PMID 33793053, 2021). "Therefore, the MIB1/ST7/IQGAP1 signaling axis is an important mediator of pancreatic cancer progression, and inhibiting MIB1 may prolong the survival of patients with pancreatic tumors." (PMID 33793053, 2021). "Thus, targeting the IQGAP1 axis may represent an attractive approach for the treatment of pancreatic cancer." (PMID 33793053, 2021). "In cell experiments, pancreatic cancer cells were grouped, and the expression levels of SOX4, MAPK1, and the phosphorylation level of IQGAP1 were detected by RT-qPCR and Western blot experiments." (PMID 38943117, 2024). "In the cytoplasm, FBP1 was found to bind with IQGAP1 to inactivate the MAPK pathway and sensitize pancreatic cancer cells to gemcitabine." (PMID 34854226, 2022). "Pancreatic cancer tissues were stained with anti-ARL4C, anti-IQGAP1, and anti-MMP14 antibodies in the serial section." (PMID 34590580, 2021). "We have recently shown that FBP1 binds the WW domain of IQGAP1, inhibiting ERK phosphorylation in pancreatic cancer cells." (PMID 33793053, 2021). "TCGA dataset showed that expression of MMP14 mRNA in pancreatic cancer patients is positively correlated with that of both ARL4C and IQGAP1 mRNA." (PMID 34590580, 2021). "Invasive pseudopods that we defined in these pancreatic cancer cells highly expressing ARL4C consisted of similar molecules, including cortactin, ARPC2, IQGAP1, and MMP14, which are involved in invadopodia functions." (PMID 34590580, 2021). "In particular, we identified that IQGAP1, a well‐known cytoskeleton regulator, was downregulated by ST7 in pancreatic cancer." (PMID 33793053, 2021). "In primary pancreatic tumors, ARL4C ASO-1316 reduced ARL4C expression at protein and mRNA levels and decreased the localization of IQGAP1 to the cell surface area." (PMID 34590580, 2021). "It has previously been reported that FBP1 inhibits the IQGAP1–ERK interaction and decreases the phosphorylation of ERK1/2 in pancreatic cancer." (PMID 30201002, 2018). "The peptides effectively blocked IQGAP1 interaction with ERK1/2, resulting in inhibition of tumorigenesis in mouse models for melanoma, breast and pancreatic cancers." (PMID 26047140, 2015). "Our research shows that the MIB1/ST7/IQGAP1 axis is essential for pancreatic cancer progression, and MIB1 inhibition may serve as a novel therapeutic strategy in patients with pancreatic cancer." (PMID 33793053, 2021). "Given that IQGAP1 can scaffold the RAS-MAPK signaling pathway, it is not surprising that IQGAP1 has an essential role in pancreatic cancer." (PMID 34439095, 2021).
pancreatic cancer (continued). "It is worth noting that FBP1 could bind to the WW domain of IQGAP1 and block IQGAP1-dependent ERK1/2 phosphorylation in pancreatic cancer." (PMID 30201002, 2018).